SCN9A (sodium voltage-gated channel alpha subunit 9)
Diseases named in the same sentence as SCN9A in open-access papers (continued):
Sharing a sentence is not in itself a finding about the gene and the disease.
primary erythromelalgia (34 papers, 2008 to 2025). "Gain-of-function mutations in the SCN9A gene, which codes for NaV1.7, are linked to severe pain conditions such as primary erythromelalgia, whereas loss-of-function mutations lead to a congenital inability to experience pain." (PMID 41357013, 2025). "Gain-of-function mutations in SCN9A, which encodes the Nav1.7 voltage-gated sodium channel, are known to cause primary erythromelalgia (PEM)." (PMID 41458489, 2025). "Multiple forms of acute hypersensitivity conditions, such as primary erythermalgia, congenital analgesia, and paroxysmal pain syndrome have been linked to polymorphisms in the SCN9A gene." (PMID 38394191, 2024). "Primary erythromelalgia is a result of an autosomal dominant mutation in the SCN9A voltage-gated sodium channel on nociceptive neurons, primarily seen in younger patients." (PMID 38978093, 2024). "The SCN9A mutations were associated with primary erythermalgia, channelopathy-associated insensitivity to pain, and paroxysmal intense pain condition." (PMID 38394191, 2024). "Two genome-wide association studies (GWAS) performed in primary erythromelalgia patients in 2004 and 2005 revealed gain-of-function mutations in the SCN9A gene." (PMID 36981004, 2023). "Gain-of-function mutations in SCN9A, the gene encoding NaV1.7, are causative of primary erythromelalgia (PE), a rare neuropathy characterised by recurring pain, warmth, and redness of the extremities." (PMID 32756358, 2020). "The first paper identified a mutation in SCN9A (the gene coding for Nav1.7) as the cause for a rare inherited pain condition known as primary erythromelalgia (PEM)." (PMID 32601768, 2020). "In comparison, gain-of-function mutations in the related SCN9A gene, which encodes NaV1.7, can result in primary erythromelalgia (PEM), either a familial or a sporadic chronic neuropathic pain syndrome." (PMID 24866741, 2014). "So far, all primary erythromelalgia (PE) SCN9A-related mutations that were characterized electrophysiologically have been located in the first three domains of Nav1.7 with the main cluster of mutations in the S4-S5 region of the second domain (DII)." (PMID 23292638, 2013). "Few detailed QST profiles have been reported in patients with primary erythromelalgia and confirmed SCN9A mutations." (PMID 23292638, 2013). "Three missense mutations, one familial (I136V) and two sporadic mutations (I848T, V1316A) of SCN9A gene were identified in Taiwanese patients with primary erythromelalgia (PE)." (PMID 23383113, 2013). "Primary erythromelalgia has been linked to mutations in SCN9A, the gene that encodes voltage-gated sodium channel NaV1.7." (PMID 18171466, 2008). "Primary erythromelalgia is often caused by mutations in the SCN9A, SCN10A, and SCN11A genes, which encode for NaV1.7, NaV1.8, and NaV1.9, neuronal sodium channels." (PMID 39458034, 2024).
Anosmia (32 papers, 2011 to 2026). An inability to perceive odors. "For example, loss-of-function mutations in the SCN9A gene, which encodes Nav1.7, result in congenital insensitivity to pain and anosmia, while preserving innocuous sensation." (PMID 39769024, 2024). "Loss-of-function mutations in SCN9A have been associated with congenital insensitivity to pain and anosmia, underscoring the potential of Nav1.7 as a genetic marker for these clinical conditions." (PMID 39769024, 2024). "The secondary symptoms associated with the respective genes differ between SCN9A (anosmia) and NTRK1 (anhidrosis)." (PMID 39156962, 2024). "Whereas CIP/HSAN-related pathogenic SCN9A variants frequently lead to anosmia as a secondary symptom, NTRK1-related neuropathy is accompanied by lack of sweat gland innervation with anhidrosis and sometimes life-threatening hyperthermia." (PMID 37769650, 2023). "Deletion of SCN9A encoding the peripheral sodium channel NaV1.7 in humans causes pain insensitivity and anosmia." (PMID 33823138, 2021). "Deletion of SCN9A encoding the voltage-gated sodium channel NaV1.7 in humans leads to profound pain insensitivity and anosmia." (PMID 33823138, 2021). "Indeed, the only additional phenotype in subjects carrying loss-of-function mutations in SCN9A was anosmia." (PMID 28848388, 2017). "The sodium channel Nav1.7 (encoded by the gene Scn9a) plays an essential role in mammalian olfaction: loss-of-function mutations in this gene cause a loss of the sense of smell (congenital general anosmia) in both mice and humans." (PMID 28420967, 2017). "Individuals with loss-of-function mutations in SCN9A cannot feel pain, and exhibit general anosmia." (PMID 25392755, 2014). "Hence a common co-phenotype in patients carrying loss-of-function variants of SCN9A is anosmia which continues to raise scientific interest in pain-focused reports." (PMID 23874707, 2013). "Loss-of-function mutations in the gene SCN9A, encoding the voltage-gated sodium channel NaV1.7, lead to congenital insensitivity to pain (CIP) and anosmia, but innocuous sensation remains intact." (PMID 33823138, 2021). "Variants in SCN9A, encoding the transmembrane voltage-gated sodium channel Nav1.7, have previously been reported in subjects with CIP accompanied by anosmia, which are typically transmitted in a recessive pattern." (PMID 30037327, 2018). "In contrast, homozygous loss of function mutations in sodium channel voltage-gated type IX, alpha subunit (SCN9A) gene has been reported to result in the CIP with an anosmia phenotype." (PMID 25309764, 2014). "Human studies have shown that homozygous or compound heterozygous loss-of-function mutations in SCN9A, the gene which encodes Nav1.7, cause congenital insensitivity to pain (CIP), which is accompanied by anosmia." (PMID 21569247, 2011). "Homozygous or compound heterozygous loss-of-function mutations in SCN9A, the gene which encodes Nav1.7, cause congenital insensitivity to pain (CIP) accompanied by anosmia." (PMID 21569247, 2011). "The clinical phenotype in humans with CIP caused by variants in SCN9A is characterized by anosmia and injuries associated with complete lack of pain sensation." (PMID 36630088, 2023). "Loss-of-function mutations in SCN9A, the gene that codes for Nav1.7 in humans, result in a congenital inability to sense pain and anosmia without affecting other sensations such as touch and temperature." (PMID 28424991, 2018). "Ex vivo electrophysiology studies in SCN9A KO olfactory sensory neurons demonstrated that the NaV1.7 mediated mechanism of action for anosmia is consistent with the mechanism responsible for absence of nociceptive perception in loss-of-function patients." (PMID 32888082, 2020). "Although patients with hereditary channelopathy-associated insensitivity to pain due to SCN9A channelopathy were reported to be otherwise healthy except anosmia, pathophysiological implications of SCN9A are not limited to pain and olfaction." (PMID 23874707, 2013).
channelopathy (27 papers, 2008 to 2026). Channelopathies are a group of diseases caused by the dysfunction of ion channel subunits or their interacting proteins. "Nevertheless, loss of function mutations in a gene family member: SCN9A, the gene encoding sodium channel α-subunit Nav1.7, lead to channelopathy-associated insensitivity to pain, with a subset of these patients also presenting anhidrosis." (PMID 34944156, 2021). "Rajasekharan Rajasekharan S S SCN9A channelopathy associated autosomal recessive congenital indifference to pain." (PMID 32100096, 2020). "Loss of function mutations in SCN9A gene causes truncation of the encoded sodium channel Nav 1.7 protein, resulting in channelopathy-associated autosomal recessive congenital insensitivity to pain." (PMID 25309764, 2014). "Thus, loss-of-function mutations in the SCN9A gene result in the truncation of the sodium channel Nav 1.7 protein, which causes channelopathy-associated autosomal recessive congenital pain sensitivity." (PMID 39403642, 2024). "Mutations in SCN9A that alter NaV1.7 function and are associated with various channelopathies leading to electrical hyperactivity of sensory neurons in the dorsal root and low reactivity of neurons in the sympathetic ganglia have been shown to be causative factors in various human pain perceptions." (PMID 36981004, 2023). "A case report SCN9A channelopathy associated autosomal recessive congenital indifference to pain." (PMID 32100096, 2020). "Mutations in the SCN9A gene are the cause of a heterogeneous channelopathy pain syndrome." (PMID 27525141, 2016). "Pelvic floor retraining with biofeedback should be considered for patients with a SCN9A channelopathy and constipation." (PMID 27525141, 2016). "Because of the inconsistent relationship between the mutation and the outcome (genotype-phenotype correlation), we and others recommend diagnosis of a specific SCN9A channelopathy based on the patient's clinical status." (PMID 27525141, 2016). "Sequence analysis revealed that channelopathy in SCN9A is a critical mediator of nociceptive pain." (PMID 36981004, 2023). "Subsequent work in murine knockout models has confirmed that SCN9A channelopathies not only contribute to increased baseline and inflammatory nociceptive thresholds, but also attenuate select chemical sensitivities and mediate itch response to specific pruritogens." (PMID 35760453, 2022). "In addition to the patient being diagnosed, four siblings have a clinical diagnosis of SCN9A channelopathy as they have consistent symptoms and a sister with a known mutation." (PMID 27525141, 2016). "In summary, we have identified two novel non-truncating mutations in SCN9A which further expands the spectrum of mutations seen in Channelopathy-associated Insensitivity to Pain." (PMID 20635406, 2010). "Two years later, sequencing of three families with congenital insensitivity to pain confirmed a channelopathy in SCN9A and therein established Nav1.7 as a key mediator of nociceptive pain." (PMID 35760453, 2022).
small fiber neuropathy (27 papers, 2011 to 2025). "Several SCN9A gain-of-function (GOF) mutations have been found in patients with small fiber neuropathy (SFN) having chronic pain, including the R185H mutation." (PMID 35769334, 2022). "The SCN9A-encoded dorsal root ganglia sodium channels' (Nav1.7) genetic variations provide an additional link between fibromyalgia and small fiber neuropathy." (PMID 29392201, 2017). "This is the first study that will be evaluating the efficacy, safety, and tolerability of lacosamide versus placebo in patients with SCN9A-associated small fiber neuropathy." (PMID 27363506, 2016). "Gain-of-function mutations in the SCN9A- gene, which codes for the Nav1.7 voltage-gated sodium channel, have been reported in small fiber neuropathy, suggesting an underlying genetic basis in a subset of patients." (PMID 27363506, 2016). "The Lacosamide-Efficacy-‘N’-Safety in Small fiber neuropathy (LENSS) study is a randomized, double-blind, placebo-controlled, crossover trial in patients with SCN9A-associated small fiber neuropathy, with the primary objective to evaluate the efficacy of lacosamide versus placebo." (PMID 27363506, 2016). "Rare missense variants have also been reported in SCN9A and SCN10A in patients with painful small fiber neuropathy." (PMID 32295642, 2020). "A wide genetic screen in patients with small-fiber neuropathy and negative for SCN9A mutations identified seven disease-causing variants in SCN10A (Familial Episodic Pain Syndrome, FEPS2; OMIM 615551)." (PMID 26236192, 2015). "The original range of inherited conditions associated with SCN9A (i.e. PE, PEPD and CIP) has recently been supplemented with chronic non-paroxysmal neuropathic pain, small fiber neuropathies (SFN) and partial congenital insensitivity to pain." (PMID 23292638, 2013).
neuropathy (24 papers, 2008 to 2024). A disorder affecting the nervous system that manifests with pain, tingling, numbness, and/or muscle weakness. "We found that SCN9A rs6746030 was associated with protection for severe neuropathy (OR = 0.39, 95% CI = 0.16–0.96; p = 0.041)." (PMID 28103821, 2017). "If these SCN9A VUSs did indeed contribute to these patients’ neuropathies, several potential explanations for their responses to immunotherapy should be considered." (PMID 32719824, 2020). "Therefore, the authors hypothesize if the expression of SCN9A and SCN3B protein is downregulated, it could inhibit the neuropathy response, such as nerve injury and nerve pain." (PMID 35436702, 2022).
diabetic neuropathy (23 papers, 2011 to 2025). A chronic, pathological complication associated with diabetes mellitus, where nerve damages are incurred due to diabetic microvascular injury involving small blood vessels that supply these nerves, resulting in peripheral and/or autonomic nerve dysfunction. "The gene-burden analysis of rare variants in our 45 target pain genes revealed significant associations with neuropathic pain in diabetic neuropathy for 2 genes: OPRM1 and SCN9A." (PMID 39471050, 2025). "SCN9A NAT correlates with the emergence of pain-related behaviors characteristic of painful diabetic neuropathy." (PMID 31680832, 2019). "Of seven rare variants in the SCN9A gene and one in the FGF13 meeting these criteria, the V1831F variant (NM_001365536.1 2:167055658_C/A c.5491G>T) in the SCN9A gene found in a painless diabetic neuropathy patient was particularly relevant." (PMID 40662354, 2025).
diabetes (16 papers, 2012 to 2025). "Multivariate analysis adjusting for diabetes mellitus did not substantially changed the association of SCN9A rs6746030 polymorphism with OXLIN (OR = 0.36; 95% CI = 0.14–0.94; p = 0.036)." (PMID 28103821, 2017).
prostate carcinoma (16 papers, 2011 to 2025). A carcinoma that arises from epithelial cells of the prostate gland. "Furthermore, a recent study found that Naringenin, a natural compound found in citrus fruits and tomatoes, reduced the invasion and proliferation of prostate cancer MAT-LyLu cells by inhibiting the activity of VGSCs encoded by the SCN9A gene." (PMID 30895169, 2019). "In addition, stimulation of mouse prostate cancer cells with nerve growth factor (NGF) upregulates the expression of Nav1.7, and in human prostate cancer cells, the promoter region of SCN9A (encoding Nav1.7) can be activated by NGF." (PMID 30895169, 2019). "SCN9A is also expressed in human prostate cancer, for which it has been proposed as a biomarker." (PMID 23874707, 2013). "It has also been reported that EGF may increase metastatic potential of prostate cancer by up regulation of SCN9A." (PMID 21314958, 2011). "EPA reliably attenuated the levels of mRNA for SCN9A and SCN8A in rat prostate cancer cell lines." (PMID 38474148, 2024).
Dravet syndrome (10 papers, 2009 to 2024). "Six out of seven of our Dravet syndrome patients with SCN9A variants harbor either missense or splice site mutations in SCN1A while a sizable portion of published SCN1A mutations are predicted to lead to truncated proteins." (PMID 19763161, 2009). "Six of these Dravet syndrome patients with SCN9A missense variants also harbored either missense or splice site SCN1A mutations and three had no SCN1A mutations." (PMID 19763161, 2009). "Of the 9 Dravet syndrome patients with SCN9A variants, six harbor either splice site or missense mutations in SCN1A." (PMID 19763161, 2009). "Singh and colleagues presented preliminary evidence that a mutation in the SCN9A gene may act as a genetic modifier of Dravet syndrome when found in conjunction with an SCN1A mutation." (PMID 32412666, 2020). "An alternate statistical approach is to examine the mutational burden of SCN9A, comparing rare (<1%) variants identified by mutational analysis of the entire coding region in all FS and Dravet syndrome populations combined versus the entire coding region in population control individuals." (PMID 19763161, 2009). "The finding of variants in both SCN1A and SCN9A in a single patient led us to investigate whether additional disease-associated alleles in SCN9A contribute to Dravet syndrome." (PMID 19763161, 2009). "In addition, we find supporting evidence for a multifactorial etiology of Dravet syndrome by uncovering concurrent variants in both SCN9A and SCN1A in a subset of our patients." (PMID 19763161, 2009). "This is indeed that case for the majority of our Dravet syndrome patients with SCN9A variants." (PMID 19763161, 2009). "Our results support the idea that some SCN9A variants when found alone might be asymptomatic or cause infrequent febrile seizures due to incomplete penetrance and variable expressivity, but likely contribute in a multifactorial fashion to Dravet syndrome." (PMID 19763161, 2009). "The shared variant, occurring in SCN9A, has been previously found in several individuals with GEFS+ and Dravet syndrome." (PMID 30642272, 2019). "SCN9A has been proposed suggested as a genetic modifier in SCN1A mutation linked with GEFS+ and as a potential susceptibility gene for Dravet syndrome." (PMID 30642272, 2019). "In an analysis of a cohort of 109 Dravet syndrome patients, 50% of whom had SCN1A mutations, we found 8 additional SCN9A variants within the transmembrane domains and intracellular and extracellular loops of Nav1.7 in 9 patients." (PMID 19763161, 2009). "None of our FS or Dravet syndrome variants overlaps with the SCN9A disease-associated changes found in the extreme pain or insensitivity to pain disorders." (PMID 19763161, 2009). "The multifactorial etiology of Dravet syndrome proposed by many investigators suggests that it is very likely that genes responsible for Dravet syndrome will far outnumber SCN1A and SCN9A." (PMID 19763161, 2009). "In the three remaining Dravet syndrome patients without SCN1A mutations, additional proconvulsive genes that act in concert with SCN9A may yet be uncovered." (PMID 19763161, 2009).
Erythema (10 papers, 2008 to 2025). Redness of the skin, caused by hyperemia of the capillaries in the lower layers of the skin. "Recently, a new SCN9A missense variant (G2567A leading to an amino acid exchange from glycine to aspartic acid at position 856) has been linked to abnormal limb development in three male family members reporting erythema and burning pain in their distal extremities." (PMID 23874707, 2013). "Analyzing the individual pain responses upon heat and mechanical stimuli with the individual mRNA expression patterns, we found a correlation between COX-2 and PGES levels at 6 h and heat evoked erythema, and identified in addition a possible role of Nav1.7 (gene SCN9A) for mechanical hyperalgesia." (PMID 22761785, 2012).
gastric cancer (9 papers, 2018 to 2025). A primary or metastatic malignant neoplasm involving the stomach. "In gastric cancer (GCa) tissue samples and in two human GCa cell lines (BGC-823 and MKN-28 cells), it was shown that the SCN9A gene, encoding NaV1.7, is the most abundantly expressed NaVα isoform." (PMID 33817575, 2021). "Previous studies have already found that high expression of SCN8A could enhance the invasion of cervical cancer cells and that SCN9A could promote gastric cancer progression." (PMID 35126466, 2021). "In addition, SCN9A was shown to possibly promote gastric cancer progression." (PMID 37910143, 2023).
osteoarthritis (9 papers, 2011 to 2026). A noninflammatory degenerative joint disease occurring chiefly in older persons, characterized by degeneration of the articular cartilage, hypertrophy of bone at the margins and changes in the synovial membrane. "Among the five SCN9A SNPs initially found to be significantly associated with pain levels in osteoarthritis, only rs6746030 results in a coding change, whereas the other four are not predicted to be detrimental." (PMID 40407611, 2025).